FOXP3 (forkhead box P3)
Diseases named in the same sentence as FOXP3 in open-access papers (continued):
Sharing a sentence is not in itself a finding about the gene and the disease.
tumor (continued). "On the other hand, Th2, Th17, and Foxp3+ regulatory T (Treg) cells are generally related to tumor development and poor prognosis." (PMID 36263125, 2022). "The Multilayer Signaling Network revealed that, in addition to HIN, fibroblasts enriched in tumours also regulate FOXP3 expression." (PMID 35608199, 2022). "A specific immune response directed against tumor cells is presumably the fundamentals both under the present Foxp3 results and the effects of modern immunotherapy." (PMID 36289746, 2022). "Foxp3-positive cells mainly assemble in hypoxic tumor regions, where cells also express high levels of HIF-1α and TGF-β." (PMID 35625561, 2022). "Flow cytometric data exhibited that lncRNA HOXA-AS2 silencing led to a significantly lower ratio of CD4+CD25+Foxp3+ cells in the tumor tissues." (PMID 35181676, 2022). "In these studies, a higher number of FoxP3+ TILs in the tumour immune milieu compared with the number of CD8+ TILs was shown to contribute to poor OS and refractoriness to chemotherapy." (PMID 35597869, 2022). "Here, we developed a score based on quantification of two TIL subsets: T helper and T reg (CD4 and FoxP3) lymphocyte subpopulations, significantly different in intraepithelial tumor component when compared to NOM." (PMID 34626165, 2022). "In this study, we examined the effect of Treg, marked by FoxP3, in EC and its tumor microenvironment." (PMID 36098901, 2022). "Mice treated with doxorubicin alone or combination treatment had lower expression of tumor PD-L1, CTLA-4, Foxp3, and tumor-infiltrating dendritic cell (CD86) proteins than did controls, with the lowest expression in mice co-treated with high-FO/Se." (PMID 36483592, 2022). "Our understanding of the mutual regulation between tumour-infiltrating FOXP3+ Treg cells and the key hallmarks in solid tumours will provide new clues for generating engineered T cells to cure cancer patients." (PMID 36569832, 2022). "Th1‐like Tregs coexpressing T‐box expressed in T cells (T‐bet) and Foxp3 are identified in the tumor tissues of human hepatocellular carcinoma." (PMID 36444617, 2022). "Although the knockout of CD36 reduces FOXP3+ Treg cells within tumours, the preservation of peroxisome proliferation activation receptor-β (PPAR-β) signal-dependent mitochondrial adaptability leads to the inhibition of tumour growth." (PMID 36569832, 2022). "The classification of BCC as a cold tumour is supported by another study showing a high stromal FoxP3+ to CD4+ T cell proportion, with a mean of 45%, concordant with our finding of 51.3%." (PMID 36552993, 2022). "In contrast to other solid tumors, high levels of tumor-infiltrating FoxP3+ Tregs were related with increased survival in CRC patients." (PMID 35655158, 2022). "In accordance with the flow cytometry results, AIL-treated tumor supernatant also inhibited the transcription of Foxp3." (PMID 36522774, 2022). "FOXP3 expression in tumor area and stroma, CD204 expression in stroma, and MHC class I in tumor area were all low among long SD patients." (PMID 36698400, 2022). "CD8+FOXP3+ is a phenotype for anti‐tumor T cells, and such cells have a similar expression profile of activated T cells." (PMID 35451108, 2022). "In preclinical studies, cancer vaccines have been shown to inhibit tumor growth and promote TILs while decreasing FoxP3+ Tregs, thereby improving the Teff/Treg ratio." (PMID 36159809, 2022). "In HCC patients, FoxP3+ Tregs are increased both in the tumor and in the periphery, and their presence in the tumor correlates with the presence of tumor macrophages." (PMID 35216137, 2022). "We further analyzed the relative percentages of activated immune cell populations (GrB+/CD8+ and OX40+/FOXP3+) in the tumor tissue from the different originating sites." (PMID 36081505, 2022). "This indicates that in this cohort, higher expression of FoxP3+ cells leads to the retention of immune cell infiltration within the tumor tissue and, consequently, poorer patient outcomes." (PMID 36139700, 2022).
tumor (continued). "CCR8 expression level in Tregs was highest in tumor tissues and higher than in FOXP3− conventional CD4 T cells (conv CD4 T cells)." (PMID 35354899, 2022). "Along with T cell mediated anti-tumor effects, BAFF also induced CD4+FoxP3+ Treg population in the spleen and tumor microenvironment." (PMID 36159874, 2022). "In this mechanism, FOXP3 likely exerts its inhibitory effects on tumor metastasis by regulating the TGF-β/Smad2/3 pathway." (PMID 36235242, 2022). "The results of FoxP3+T cell immunofluorescence staining showed that the FoxP3+T cell content in the tumor tissue of osimertinib combined with the bevacizumab group was lower than that of the osimertinib single-agent group." (PMID 35783156, 2022). "Tregs are an immunosuppressive subset of CD4+ T cells characteristically expressing CD4, CD25, and FOXP3, and exhibit diversity and functional heterogeneity across tumor types." (PMID 36532071, 2022). "CD8+ and CD4+ T cell numbers in tumors increased dramatically in combination treatment group while shown a decrease of Treg cells (Foxp3+) when compared with other groups in the tumor." (PMID 36329529, 2022). "In particular, CD4(+) Tregs expressing the transcription factor forkhead box P3 (FOXP3) are abundant in tumor tissues, where they appear to hinder the induction of effective antitumor immunity." (PMID 35358193, 2022). "Tregs, characterized by lineage-specific Foxp3 expression, are critical to suppress excessive immune responses to maintain homeostasis, however, in favor of tumor progression." (PMID 35935577, 2022). "Nevertheless, functionally different subgroups of tumor-infiltrating FoxP3+ Tregs contribute in opposing ways to determining CRC disease prognosis." (PMID 35655158, 2022). "Several studies have reported compelling evidence that tumour cells produce various cytokines and chemokines to promote the proliferation of Tregs and induce FOXP3– T cells into FOXP3+ Tregs." (PMID 35969010, 2022). "A number of studies reported that CD4+Foxp3+ regulatory T cell frequency was significantly higher in peripheral blood and tumor tissues of patients with HNSCC than in healthy controls and it was correlated with progression of HNSCC." (PMID 36376825, 2022). "Immunohistochemical results showed that FoxP3 was highly expressed in metastatic lung cancer tumor tissues." (PMID 35783156, 2022). "Exosomes derived from the tumor caused the expansion of Tregs, inducing the generation of Tim3(Low) Treg with increased expression of CD25 and FOXP3." (PMID 36233088, 2022). "In the patients with the number of liver metastases > 1, the decrease of PD-L1 and the increase of regulatory T cells (Foxp3) both suggested enhanced immunosuppression in the tumor microenvironment." (PMID 36195882, 2022). "Higher percentages of tumor‐infiltrated FOXP3+ Helios− Tregs were seen in advanced‐stage NSCLC with poorer survival." (PMID 35474948, 2022). "Among these T cells, FOXP3+ Tregs play pivotal roles in the progression of steatohepatitis and in creating pre-tumor microenvironment settings." (PMID 35912096, 2022). "To exclude that depletion of half of the Treg compartment results in the rejection of tumor cells, we additionally generated mixed bone chimeric mice of FoxP3.Luci-DTR and WT bone marrow cells." (PMID 34423375, 2022). "With FOXP3 knockout, tumor cells secreted less IL-10 and TGF-β1, and T-cell survival was significantly upregulated, suggesting that FOXP3 plays an important role in malignant phenotypes, particularly during invasion and immune escape." (PMID 36185217, 2022). "For example, the increased infiltration of CD8-positive lymphocytes into tumor tissues was reported to be associated with better clinical outcome of the patients, whereas that of CD4- and Foxp3-positive lymphocytes with their worse prognosis." (PMID 35565281, 2022). "Patients with DCB presented also with more DC-LAMP+ dendritic cells, CD3+ T cells and FOXP3+ Tregs in baseline tumor biopsies." (PMID 35794623, 2022).
tumor (continued). "PD-L1CPS was higher in tumor-infiltrating immune cells (r = 0.387, p = 0.001) and positively correlated with programmed cell death-1 and forkhead box P3 + regulatory T cell (FOXP3 + Treg) infiltration (r = 0.443, p < 0.001; r = 0.532, p < 0.001)." (PMID 36376881, 2022). "The association between tumor-infiltrating CD8+ CTLs, CD163+ M2 TAMs, Foxp3+ Tregs and clinicopathological features." (PMID 34733785, 2021). "In vivo tumor models demonstrated that GO-Y030-treatment prevented tumor growth and reduced the Foxp3+ Tregs population in tumor-infiltrating lymphocytes." (PMID 34248973, 2021). "This study showed increased numbers of CD8+ cells by IHC and decreased CD4+ CD25+ FoxP3+ Tregs in ER-tumours in mice treated with SERDs." (PMID 34602068, 2021). "In contrast, FOXP3 was found highly expressed in tumor cells than in corresponding epithelial cells, being proposed its involvement in the biology of cancer." (PMID 34484217, 2021). "We need to better understand the function of FoxP3+Treg cells and their different biological characteristics in the tumor." (PMID 34654443, 2021). "We found that FOXP3 expression impaired tumor cell growth in vitro as well as in vivo when the cells were injected subcutaneously into BALB/c mice." (PMID 33671179, 2021). "Flow cytometric analysis showed increases in regulatory T cells (Tregs) in lymph nodes in CCL17 TG mice with high mRNA levels of IL-10 and Foxp3 in tumors, suggesting that Tregs attenuated tumor immunity." (PMID 33670758, 2021). "Conversely, many studies have established tumor-infiltrating Foxp3+ Tregs as a prognostic indicator of a favorable clinical outcome in CRC patients." (PMID 33527196, 2021). "The frequencies of CD8+ T cells (CD45+ CD3+ CD11b- CD4- CD8+) and Foxp3-CD4+ T cells (CD45+ CD3+ CD11b- CD4+ CD8- Foxp3-) in CT-26 tumor tissues were significantly higher than those in Colon 26 tumor tissues." (PMID 34774008, 2021). "BT942, daclizumab and the combination all reduced the proportion of Foxp3+(Treg) and hCD25+Foxp3+ cells percentage in the tumor." (PMID 34824364, 2021). "Immune checkpoint blockade enhanced the efficacy of TA99, which was associated with greater CD8+/Foxp3+, NK1.1+ and dendritic cell infiltrates, suggestive of an increased anti-tumor innate and adaptive immune responses." (PMID 33520112, 2021). "When Foxp3 is over-expressed in the local tumor microenvironment, it helps tumor cells escape the surveillance of the immune system and promotes tumor growth." (PMID 33784955, 2021). "The 32 samples were also subjected to analysis of CD20, CD4, CD8, CD68, Foxp3 and P16 by multiplex immunofluorescence (mIF) staining, and the immune markers were evaluated in the tumor body (TB), tumor margin (TM) and normal stroma (NS) regions separately." (PMID 35145511, 2021). "High post-treatment stromal CD8+ TILs numbers were found strongly correlated with better prognosis, and a high pre-treatment intraepithelial CD8/FoxP3 ratio was found to be a predictor of tumour regression." (PMID 34321074, 2021). "There was a trend towards a lower proportion of CD4+FoxP3+ regulatory T-cells in the tumor microenvironment of patients exposed to anti-PD-1 compared to control patients (p = 0.0571)." (PMID 34771650, 2021). "In this regard, in vivo melatonin administration mediates the downregulation of Foxp3 in Tregs, thus decreasing Treg infiltration in tumor areas as well as reducing tumor growth." (PMID 33535472, 2021). "For instance, Th17 cells have been shown to progressively transdifferentiate into IL-17A+FOXP3+ and IL-17A–FOXP3+ T cells during tumor development." (PMID 34026764, 2021). "Tumor cells and the components of TME, including CD8+ T cells, CD4+ T cells, NK cells, dendritic cells, B cells, macrophages, FOXP3, and Collagen I have close correlations to tumor treatment and prognosis." (PMID 34239944, 2021).
tumor (continued). "Conversely, USP7 knockdown results in the instability of Foxp3, which subsequently impairs the immunosuppressive function of Treg, and promotes tumor suppression mediated by the immune system." (PMID 34869041, 2021). "Based on those finds, they demonstrated that Foxp3 suppressed tumor growth in mouse tumor models by directly or indirectly inhibiting oncogene c-Myc." (PMID 34566989, 2021). "In NSCLC, about 70% of Tim-3+ CD4+TILs expressed Foxp3, and about 60% of Foxp3+ tumor infiltrating lymphocytes were Tim-3 positive." (PMID 34631560, 2021). "Recruitment of CD4+Foxp3+ Tregs to the tumor bed is an important mechanism by which tumors evade immune surveillance." (PMID 34676831, 2021). "The results showed that FOXP3+ and IL-21+ cells collocated in the same area in the tumor stroma and that the increased density of the IL-21+ cells was positively correlated with that of the FOXP3+ cells." (PMID 34026621, 2021). "Among this tumor subset, the expression levels of PD-1 and FOXP3 showed a moderate positive correlation." (PMID 35052695, 2021). "As the Treg marker FOXP3 message levels were higher in both tumor types than in normal controls, the results have indicated an actively immunosuppressive microenvironment in both MNG and GBM." (PMID 35366268, 2021). "Regulatory T-cells (Tregs) represent a critical subset of CD4 T-cells, characterized by CD4 + CD25+ Forkhead box P3+ (FoxP3+) phenotype, able to control peripheral tolerance and responses to foreign and tumor antigens." (PMID 34640606, 2021). "Upon statistical analysis, on comparing the CD8 and FoxP3 counts in the tumor vs. non-tumor regions in the cohort, we observed a lower CD8 count (p = 0.034) and a higher FoxP3 count (p=<0.0001) in the tumor region." (PMID 34257613, 2021). "In line with it, an independent study demonstrates that MDSCs from tumour-bearing mice compromise TGFβ-induced Foxp3+CD4+CD25+ Treg differentiation in a ROS-dependent manner." (PMID 33941245, 2021). "Together these data indicate that the CHK1i+LDHU combination promotes strong anti-tumour immune responses, but this appeared to be blunted in the tumour microenvironment by T cell exhaustion and immunosuppressive signals from Tregs and FoxP3+NKT cells." (PMID 34359633, 2021). "By secreting the suppressive cytokines IL-10, IL-35 and TGF-β, Bregs suppress CD4+ T cell proliferation and promote Foxp3 expression in Tregs, thereby favoring immunosuppression and tumor development." (PMID 34681881, 2021). "To evaluate the antitumoral effect of FOXP3, we transfected the 4T1 tumor cells with the plasmid pcDNA-FOXP3 for the stable expression of FOXP3." (PMID 33671179, 2021). "Immunohistological sections of the lungs were made and stained for FoxP3 to evaluate the tumor micro-environment and overall histology of the nodules." (PMID 33828163, 2021). "Regulatory T cells (Tregs), which express the CD4, CD25 and FOXP3 phenotypes, are found in tumour microenvironments and induce immune tolerance as they downregulate CD4 helper and CD8 cytotoxic T cells." (PMID 34206956, 2021). "Given that IL-21 plays a positive role in PD-L1-induced Treg generation, we next investigated the relationships between the expression patterns of IL-21, PD-L1, and FOXP3 in tumor specimens." (PMID 34026621, 2021). "Tumor cell vaccine plus FOXP3 gene silencing inhibits tumor growth and enhances the efficacy of vaccination immunotherapy." (PMID 34806028, 2021). "Each tumor section was stained simultaneously for a panel of seven markers, including CD3, CD8, and FoxP3 T cell-associated markers, cytokeratin to label epithelial tumor cells and DAPI for nuclei detection." (PMID 33498681, 2021). "Tregs (CD4+ CD25+ Foxp3+) are involved in tumor development and progression by inhibiting anti-tumor immunity in the TME." (PMID 34867958, 2021).
tumor (continued). "Aa decrease in Treg cell FOXP3 expression would destabilise the Treg cell phenotype and attenuate their suppressive activity and enhance immune responses to tumours in patients with cancer." (PMID 34408239, 2021). "In particular, the CD4+ regulatory T cells (Tregs) expressing the transcription factor Foxp3 are highly immune suppressive and promote tumour progression by suppressing effective anti-tumour immunity." (PMID 33451015, 2021). "The expression intensities of programmed death-ligand 1 (PD-L1), CD4, CD8, CD20, FoxP3, and CK in whole tumor tissues were evaluated." (PMID 34502561, 2021). "We simultaneously stained the tumor sections with Foxp3, CD30, and OX40, and then determined the numbers of CD30+OX40−, CD30−OX40+, and CD30+OX40+ Tregs." (PMID 33527196, 2021). "CD4+FOXP3+ regulatory T cells (Tregs), a suppressive subset of T cells, can impair anti-tumor responses and reduce the efficacy of currently available immunotherapies." (PMID 34712661, 2021). "The CpG in the promotor region of FOXP3 of all the tumor samples were hypomethylated (highlighted as red box) while there was increased methylation in the gene body." (PMID 34012510, 2021). "Although FOXP3 was previously reported to promote tumor growth and metastasis in NSCLC, there were also researches asserting that tumoral FOXP3 had the potential to suppress tumor function in SqCLC." (PMID 34992605, 2021). "Repeating this process 100 times we attain average pairwise classification accuracies: CD8+ vs. FoxP3+ 74.7%, CD8+ vs. CD68+ 65.3%, and FoxP3+ vs. CD68+ 86.3% (see tumor TC in SI Appendix)." (PMID 34625491, 2021). "Treg (CD4+/CD25+/Foxp3+) are immunosuppressive cells in the tumor microenvironment and correlates with tumor progression also in HCC." (PMID 34282787, 2021). "Using excisional biopsies, the authors found that 81% of samples had detectable tumor-infiltrating lymphocytes, with 51% positive for FoxP3+ Tregs." (PMID 34141625, 2021). "Regulatory T cells, which express FOXP3, promote tumor growth by inducing host tolerance against tumor antigens by attenuating the T cell-mediated immune response against the tumor cells and enabling them to evade the antitumor immune response." (PMID 34858823, 2021). "Multiplex IHC images showed that mice receiving TPX therapy displayed reduced tumor-infiltrating Arg1+ M2 macrophages and Foxp3+ Treg cells, whereas the frequency of CD8+ cytotoxic T lymphocytes was not changed." (PMID 33809137, 2021). "Specific subsets of lymphocytes were also analysed (CD3, CD4, CD8, CD45R0, and FoxP3 cells) within different tumour locations (tumour center, invasive margin, and stroma)." (PMID 34940086, 2021). "As an important regulator of tumor microenvironment, TIPE2 was found to significantly inhibit oncogenic progression through activating T and NK cells, and inhibiting FoxP3+ Treg cells in tumor microenvironment." (PMID 34249724, 2021). "Herein, we analyzed the presence of lymphocyte infiltrates (CD3+, CD8+, or FoxP3+ T lymphocytes) inside the tumor and the tumor invasive margins of CRC samples to evaluate their prognostic potential." (PMID 34440038, 2021). "The fraction of proliferating (Ki67+) cells for all four immune cell subpopulations (CD3+, CD4+, CD8+, Foxp3+) was numerically higher in basal-like tumours, whereas luminal tumours showed the lowest fraction of proliferating cells." (PMID 33742063, 2021). "The PD-1-PD-L1 interaction directly inhibits anti-tumor T cells responses, promotes peripheral effector T cell exhaustion and enhances Foxp3 expression in Th1 cells." (PMID 33571254, 2021). "EcN associates with Galunisertib through increasing the levels of IFN‐γ+ CD8+ cells and DCs in tumor‐draining lymph modes along with attenuating Foxp3+ Tregs and IL‐10 in tumors." (PMID 34026439, 2021). "In none of the patients, either before or under therapy, we were able to detect relevant numbers of FOXP3+ regulatory T cells infiltrating the tumor." (PMID 33275172, 2021).